LINC01378 (long independently transcribed non-coding RNA 1378)
Synonyms: LINC02263
Gene: Long non-coding RNA gene on chromosome 4 (117,360,565 to 117,691,188, forward strand). Ensembl gene ENSG00000236922.
Diseases named in the same sentence as LINC01378 in open-access papers:
LINC01378 is named in the same sentence as 1 disease in open-access papers, as found by Europe PMC text mining. Sharing a sentence is not in itself a finding about the gene and the disease.
LINC01378 shares sentences with these, for which no sentence is quoted: Alzheimer disease (1 paper).